ACTA2 (actin alpha 2, smooth muscle)
Diseases named in the same sentence as ACTA2 in open-access papers (continued):
Sharing a sentence is not in itself a finding about the gene and the disease.
aortic aneurysm (19 papers, 2015 to 2024). A ruptured aneurysm located in the wall of the proximal portion of the descending aorta proceeding from the arch of the aorta. "The ACTA2 gene was the causative gene detected in approximately half of cases of nonsyndromic hereditary aortic aneurysms and dissections." (PMID 38919319, 2024). "Adding the causal gene, ACTA2, to list 5+ (n = 19+1) revealed MYH11 with ACTA2 to be associated with Aortic Aneurysm (HP:0004942, q = 2.313x10-3), Aortic Dissection (HP:0002647, q = 5.629x10-3), and Aneurysm (HP:0002647, q = 8.754x10-3)." (PMID 39480826, 2024). "This study identified a previously unreported heterozygous variant, G148R, in the ACTA2 gene, manifesting in a patient with non-syndromic aortic aneurysm presenting with MSMD." (PMID 38316882, 2024). "In aortic aneurysms, mutations in ACTA2 have been linked to weakening and expansion of the aortic wall." (PMID 38685981, 2024). "Many genes have been implicated in the etiology of non-syndromic aortic aneurysm such as ACTA2, MYH11, FLNA, and SMAD3." (PMID 38404628, 2023). "ACTA2 mutations predispose to development of aortic aneurysms and early onset coronary and cerebrovascular disease." (PMID 26637293, 2015). "ACTA2 encodes vascular smooth muscle actin, abnormalities of which cause dysfunction of smooth muscle cells in the aortic tunica media and, in turn, lead to aortic aneurysms and dissections." (PMID 38919319, 2024). "In humans, heterozygous ACTA2 mutations predispose individuals to aortic aneurysm." (PMID 28848449, 2017). "In addition to aortic aneurysms, other features associated with subset of families with ACTA2 mutations include cases with BAV and a predisposition for occlusive vascular diseases, including thrombotic stroke and coronary artery disease." (PMID 28848449, 2017). "The relative expression level of the contractile marker ACTA2 decreased to 0.307 (p < 0.001) in the aortic aneurysm model, while the expression level of CD68 increased to 54.85 (p < 0.001)." (PMID 37189183, 2023). "ACTA2-related vasculopathy is an autosomal dominant genetic disorder characterized by aortic aneurysms and dissection, and limb artery lesions are rare." (PMID 34630793, 2021). "Mutations in ACTA2 and MYH11 disrupt proteins involved in SMC contraction and result in predisposition to aortic aneurysms and dissections." (PMID 27586135, 2016). "In latter case, mutations in smooth muscle actin (ACTA2) and smooth muscle myosin (MYH11) cause PDA associated with aortic aneurysm." (PMID 25861618, 2015). "Previous reports have indicated that the amino acid residue G148 in ACTA2 can cause inherited aortic aneurysms and dissections, but the details were not well described." (PMID 38316882, 2024). "Also, the ACTA2 variant in heterozygosity can lead to a broad picture of vascular pathology, which includes MMD, along with aortic aneurysms, aortic dissection and premature CAD." (PMID 38790247, 2024). "However, the presence of some (i.e., one allele) wild-type SMα-actin appears to be sufficient to regulate vascular tone to prevent aortic disease in Acta2R149C/+ mice in contrast to Acta2−/− mice that lack SMα-actin and develop aortic aneurysm with age." (PMID 37298565, 2023). "In patients with MYH11 variants, the effect of intronic variants on splicing was classified into pathogenic or nonpathogenic variants in aortic aneurysms, so as to ACTA2 variants." (PMID 33083483, 2020). "The aim of our study was to assess the frequency of ACTC1 mutations in patients with sporadic cases of ASDII and the frequency of ACTA2 mutation in patients with isolated PDA without aortic aneurysm." (PMID 25861618, 2015). "Although it has been demonstrated that mutations affecting the contractile unit, such as ACTA2 and MYH11-gene mutations, contribute to the formation of thoracic aneurysms or dissections, still, little is known about the loss of VSMC contractile function in the pathogenesis of aortic aneurysm." (PMID 34572274, 2021).
aortic aneurysm (continued). "It is still unknown, however, whether ACTA2 gene mutations can be associated with isolated cases of PDA without aortic aneurysm." (PMID 25861618, 2015). "Moreover, pathogenic mutations in several genes have been related to non-syndromic CHD with PDA being a prominent phenotype, including FLNA-related PDA and periventricular heterotopia and MYH11/ACTA2-related PDA and aortic aneurysm." (PMID 36010266, 2022).
pancreatic cancer (19 papers, 2017 to 2025). "Aberrant ACTA2 expression is associated with poor clinical outcomes in lung and pancreatic cancers." (PMID 28881584, 2017). "Common markers, such as Acta2, Mki67 and Krt19, were expressed in specific subpopulations, confirming the pancreatic cancer cell identity." (PMID 40621620, 2025). "Conditional Prrx1 loss of function in Sm22 (Tagln) positive CAFs in a mouse model of pancreatic cancer also promoted in vitro an activated phenotype with an increase in ACTA2 and COL1 expression levels." (PMID 37261432, 2023). "DES, defined as the intermediate filament protein in striate muscle, is highly expressed in pancreatic cancer patients, and co-expression of ACTA2 and DES is positively correlated with lymph node metastasis." (PMID 36406134, 2022). "Aberrant expression of ACTA2 has poor clinical outcomes in different cancers, including breast, lung, and pancreatic cancers." (PMID 35805203, 2022). "These analyses revealed that FAP expression in CRC is most closely related to FAP- and ACTA2-expressing stromal cells in pancreatic cancer (R2 = 0.53 and 0.55, respectively) and least to inflammatory CAFs (R2 = 0.06)." (PMID 35296803, 2022). "A high proportion of cells in both breast and pancreatic cancers expressed α-SMA (Acta2)." (PMID 32455670, 2020). "Interestingly, vimentin (VIM) and αSMA (ACTA2) that we showed to co-localize with integrin α11 in the pancreatic cancer tumors also displayed increased expression in this tumor tissue." (PMID 31159419, 2019). "Increased ACTA2 expression mediates the epithelial-mesenchymal transition (EMT) that is implicated in tumor progression and metastasis during cancer development in lung and pancreatic cancers." (PMID 28881584, 2017). "More cells with stronger staining of ACTA2 and FAP were found in a MICAL2high patient with pancreatic cancer compared with a MICAL2low patient." (PMID 38326344, 2024). "As reported, c8 was defined as antigen-presenting CAFs (CAFap) that overexpressed ACTA2, HLA-DRA, and CD74 55 and was enriched in pancreatic cancer." (PMID 36333338, 2022). "COL1A1, COL1A2, ACTA2, PDGFRB and FAP displayed a significant positive correlation with this gene dataset in melanoma tumours (SKCM), whereas in pancreatic tumours (PAAD), that correlation was even stronger owing to their highly desmoplastic TME." (PMID 35654839, 2022). "We further investigated this and, in accordance with our findings in pancreatic cancer biopsies and mouse pancreatic cancer models, we also identified TGFBI transcript in some of the ACTA2-expressing fibroblasts in the stroma of ovarian and omental metastasis." (PMID 34561272, 2021). "The iCAF subpopulation is detected in invasive pancreatic cancer, and iCAFs exhibit elevated expression of VIM, FAP, COL3A1, DES, IL6, and CXCL12 and reduced expression of ACTA2 (coding α-SMA)." (PMID 33333727, 2020). "Besides, the mRNA expression of FERMT2 positively correlated with ACTA2, COL1A1, FAP, and FSP based on TCGA pancreatic cancer data." (PMID 38910148, 2024). "Although a large proportion of fibroblasts in pancreatic cancer tissues appear to express ACTA2, not all fibroblasts are detectable by an anti-ACTA2 antibody." (PMID 35805064, 2022).
fibrosis (17 papers, 2017 to 2025). the formation of excess fibrous connective tissue in an organ or tissue in a reparative or reactive process. "Collectively, these data indicate CREBBP/EP300 is a highly associated pathway in localized human fibrosis that controls key aspects of myofibroblast phenotype and function, including ACTA2 and COL1A1 gene expression and cell contractility." (PMID 32759223, 2020). "The extent of liver granuloma and fibrosis was evaluated by monitoring the liver aspect, collagen deposition (Sirius red staining), and HSCs activation [high RNA and protein expression levels of Acta2 (which encodes α-SMA), Col1a1, and Col3a1]." (PMID 29321784, 2017). "The Pde4d, Col1a1, and Acta2 were also upregulated in carbon tetrachloride–induced (CCl4-induced) fibrosis." (PMID 41196648, 2025). "Isolation of primary cells from bleomycin-induced fibrosis lung showed a good correlation of Gremlin2 and Acta2 (α-SMA) expressions." (PMID 34422900, 2021). "qPCR analysis showed a decrease in highly upregulated gene levels associated with HSC activation, namely Acta2, Col1a2, Col3a1, TIMP-1, TGF-b, and PDGFR-b, in the neratinib-treated group compared to that in the vehicle-treated fibrosis group." (PMID 32901093, 2020). "Importantly, GDF10 expression was significantly elevated in human metabolic liver disease and fibrosis samples, showing strong correlation with classic fibrosis markers (ACTA2, COL1A1)." (PMID 41281741, 2025). "Downregulation of Acta2/α-SMA must be interpreted within neonatal pathobiology: unlike adult fibrosis, neonatal hyperoxia primarily disrupts fibroblast subtype dynamics and alveolar septation rather than inducing classical collagen-rich fibrosis." (PMID 41462696, 2025). "Compared with sham rats, 5/6NX rats showed significantly increased levels of SCr, BUN, and HA, as well as increased fibrosis area, glomerular sclerosis index, and fibrotic marker levels (COL1A1, VIM, and ACTA2), suggesting that the 5/6NX rat model was effective." (PMID 32854194, 2020). "Interestingly, the fibrosis markers (Vim, Acta2 and Postn) and ECM genes (Col1a2, Col3a1 and Fn1) were upregulated in YB-1 knockdown mice, demonstrating that knockdown of YB-1 promotes cardiac fibrosis and ECM remodeling." (PMID 31588235, 2019). "Indeed, exposure of PCLS from patients with fibrosis or end-stage cirrhosis to Ac-6-FP resulted in a decrease in MAIT cell activation and reduced the expression of fibrogenic genes, including COL1A1 and COL1A2, ACTA2, and TGFB1, together with the number of fibrogenic cells." (PMID 37005415, 2023).
multisystemic smooth muscle dysfunction syndrome (16 papers, 2015 to 2026). "Multisystemic smooth muscle dysfunction syndrome (MSMDS) is a rare disorder caused by ACTA2 mutations, including the R179H variant, which alters actin filament stability and dynamics and smooth muscle contractility." (PMID 41493807, 2026). "Multisystemic smooth muscle dysfunction syndrome (MSMDS) is an autosomal dominant disorder caused by mutations in the ACTA2 gene, resulting in variable clinical manifestation and multi-organ dysfunction." (PMID 39867662, 2024). "Multisystemic smooth muscle dysfunction syndrome (MSMDS) is an autosomal dominant disorder caused by mutations in the ACTA2 gene, which encodes vascular smooth muscle α-actin (SM α-actin)." (PMID 39867662, 2024). "This functional relationship explains the phenotypic similarities between Multisystemic Smooth Muscle Dysfunction Syndrome caused by ACTA2 mutations, and Megacystis-Microcolon-Intestinal Hypoperistalsis Syndrome 2 caused by MYH11 mutations." (PMID 39480826, 2024). "Multisystemic Smooth Muscle Dysfunction Syndrome is caused by a mutation in the ACTA2 gene and affects fewer than one in a million people." (PMID 39480826, 2024). "Mutations in ACTA2 cause a variety of vascular diseases, including thoracic aortic disease, coronary artery disease, stroke, and multisystemic smooth muscle dysfunction syndrome." (PMID 35754816, 2022). "The three pathogenic variants were identified in the genes ACTA2 (multisystem smooth muscle dysfunction syndrome), PKHD1 (autosomal recessive form of polycystic kidney disease), and PKD1 (autosomal dominant polycystic kidney disease type 1)." (PMID 32779812, 2020). "However, vascular abnormalities, including ascending aortic aneurysms, have been described in patients with multisystemic smooth muscle dysfunction syndrome (MSMDS) that is caused by mutations in the ACTA2 gene, encoding α-SMA." (PMID 35802750, 2022). "Moreover, p.R179H mutation in ACTA2 gene is the main cause for multisystemic smooth muscle dysfunction syndrome (MSMDS) and accordingly facilitates in genetic counseling and reduces reproductive hazards." (PMID 32779812, 2020). "Moreover, Acta2 is one of 6 different actin isoforms and is involved in the contractile apparatus of smooth muscle; mutation in this gene can cause a variety of vascular diseases, such as multisystemic smooth muscle dysfunction syndrome." (PMID 37731819, 2023). "The Actin alpha 2 (ACTA2) gene is widely expressed in most cells, and its mutations have been found to cause a variety of vascular diseases, such as thoracic aortic disease, coronary artery disease, stroke, moyamoya disease, and multisystem smooth muscle dysfunction syndrome." (PMID 34858981, 2021). "Congenital mydriasis and retinal arteriolar tortuosity are associated with the life-threatening multisystemic smooth muscle dysfunction syndrome (MSMDS) due to mutations in the gene, ACTA2, which encodes alpha-smooth muscle actin (α-SMA)." (PMID 32093627, 2020). "To develop a comprehensive therapy for multisystemic smooth muscle dysfunction syndrome, we used CRISPR (clustered regularly interspaced short palindromic repeats)–Cas9 (CRISPR-associated protein 9) adenine base editing to correct the ACTA2 R179H sequence variant." (PMID 40378078, 2025). "Also, specific variants of ACTA2 have been implicated in the Multisystemic Smooth Muscle Dysfunction Syndrome (OMIM 613834), indicating that ACTA2 plays important roles in the smooth muscle of non-vascular tissues." (PMID 29202781, 2017).
Stroke (16 papers, 2015 to 2025). Sudden impairment of blood flow to a part of the brain due to occlusion or rupture of an artery to the brain. "Specific ACTA2 mutations have also been linked to an increased risk of early-onset stroke or coronary artery disease." (PMID 38685981, 2024). "ACTA2 pathogenic variants altering arginine 179 cause childhood-onset strokes due to moyamoya disease (MMD)-like occlusion of the distal internal carotid arteries." (PMID 37886459, 2023). "Other ACTA2 mutations predisposing to stroke have been reported, such as those resulting in R258C/H and R39H changes." (PMID 26637293, 2015). "A subset of ACTA2 pathogenic variants predispose to early-onset stroke or coronary artery disease." (PMID 35896809, 2023). "We observed stroke in the setting of the mutation altering R117 in our Chinese population as well, and this finding further supports that ACTA2 mutation may be responsible for stroke in TAAD patients." (PMID 27431987, 2016). "Structural modeling of R179H and other ACTA2 mutations involved in the stroke syndrome showed a common positioning on the actin inter-strand surface responsible for F-actin double strand bundling, providing a molecular basis for the new ACTA2-related cerebrovascular disease (ARCD) entity." (PMID 26637293, 2015). "Interestingly, heterozygous missense mutations in ACTA2 can result in a variety of other vascular diseases including strokes, early onset coronary artery disease and Moyamoya disease, indicating that structural weakness of vessels is unlikely to be the only manifestation of such mutations." (PMID 29202781, 2017). "In addition, the systemic analysis of intracranial arteries by iCafe could have utilities in clinical studies of vascular disease states, such as Moyamoya or mutations in the skeletal muscle α-actin gene (ACTA2) in children and cardiovascular disease or strokes in adults." (PMID 34122310, 2021). "Although rare, genetic disorders as ACTA2 variants are important to consider especially in juvenile and familial stroke cases which are not sufficiently explained by conventional risk factors." (PMID 37587538, 2023). "Apart from pathogenic or likely pathogenic findings, 41 rare VUS in 325 stroke-related candidate genes were detected in 39 probands, including eight novel variants: ABCA1 p.H1223P, ACTA2 p.N298S, COL5A1 p.P930R, FBN1 p.Q514E, FBN1 p.K1052T, GP1BA p.P437*, RNF213 p.N1631Efs*34, and TSC1 p.P397del." (PMID 36580209, 2023). "Our study shows that NR attenuates cerebrovascular disease associated with the Acta2 R179C mutation after LCAL by not only decreasing occlusive lesions in the injured carotid artery, but also increasing cerebral blood flow and decreasing deaths due to stroke." (PMID 37886459, 2023). "A subset of ACTA2 mutations also cause early onset coronary artery disease (CAD) and stroke." (PMID 26637293, 2015). "qPCR of RiboTag-IP’dmRNA from isolated microvessels after stroke revealed enrichment of astrocyte markers Aqp4 and Gfap, as well as depletion of vascular markers including Pecam1, Cldn5 (endothelial cells), Pdgfrb (pericytes), and Acta2 (vascular smooth muscle cells)." (PMID 39796165, 2025).